Y_RNA (Y RNA )
Gene: Miscellaneous RNA gene on chromosome 9 (61,883,640 to 61,883,751, reverse strand). Ensembl gene ENSG00000238749.
Homologues: Orthologues: chimpanzee Y_RNA (100% identical), macaque Y_RNA (91% identical). Paralogues in human: Y_RNA (100% identical), Y_RNA (99% identical), Y_RNA (98% identical), Y_RNA (97% identical), Y_RNA (95% identical), Y_RNA (88% identical), RNY1P5 (87% identical), Y_RNA (87% identical), Y_RNA (86% identical), Y_RNA (85% identical), Y_RNA (84% identical), RNY1 (83% identical), and 101 more.